FBN1 (fibrillin 1)
Diseases named in the same sentence as FBN1 in open-access papers (continued):
Sharing a sentence is not in itself a finding about the gene and the disease.
Marfan syndrome (continued). "In patients with Marfan Syndrome (MFS) mutation of the fibrillin-1 gene (FBN1) leads to defective extracellular microfibrils, resulting in divergence and instability of the entire connective tissue." (PMID 26840980, 2016). "Marfan syndrome is a variable autosomal dominant disease caused by mutations in the fibrillin-1 gene on chromosome 15." (PMID 28050285, 2016). "For example, FBN1 encodes a fibrillin family protein associated with Marfan syndrome and contains large-effect mutations for height that are explained by allelic heterogeneity." (PMID 27444743, 2016). "Marfan syndrome, with a prevalence of 1:5000, is in most cases due to a mutation in the fibrillin-1 gene (FBN1)." (PMID 27376074, 2016). "In a mouse model of Marfan’s syndrome, fibrillin-1 deficiency was associated with increased TGF-beta signaling, which is thought to contributes to the development of aortic aneurysm." (PMID 27646033, 2016). "For example, fibrillin-1 (FBN1) mutations cause Marfan syndrome (OMIM 154700) and ocular abnormalities including ectopia lentis, myopia and glaucoma." (PMID 27484908, 2016). "While mutations in the gene for fibrillin-1 cause Marfan syndrome, there is limited data of association between Marfan syndrome and risk of testicular germ cell tumors." (PMID 27487789, 2016). "This is a critical step in tissue homeostasis, evidenced by mutations in fibrillin-1, which result in Marfan syndrome." (PMID 28116125, 2016). "Mice carrying a cysteine substitution mutation in Fibrillin-1 (Fbn1) serve as a model for Marfan Syndrome." (PMID 26527432, 2015). "Increased TGF- β1 levels are associated with Marfan syndrome (MFS) caused by FBN1 mutations and subsequent defects in signaling system." (PMID 26103587, 2015). "The sequence of MUA-3 shares high homology with that of the human FBN1, mutations in which are the cause of Marfan syndrome." (PMID 25917920, 2015). "Although WES did not identify the cause of the primary clinical features, it importantly identified a de novo FBN1 mutation which gave the patient a secondary genetic diagnosis of Marfan syndrome." (PMID 26284228, 2015). "Marfan syndrome results from mutations in the fbn1 gene, which encodes an extracellular matrix (ECM) glycoprotein, Fibrillin-1 (FBN1)." (PMID 25917920, 2015). "Mutations in the FBN-1 gene, which encodes the extracellular matrix protein, fibrillin-1, were identified as the cause of Marfan syndrome in a number of families, and modern DNA sequencing techniques can now identify FBN-1 mutations in up to 92% of patients." (PMID 25965707, 2015). "Pathogenic mutations in FBN1, encoding the glycoprotein, fibrillin-1, cause Marfan syndrome (MFS) and related connective tissue disorders." (PMID 26684006, 2015). "Mutations in the gene for fibrillin-1 cause the Marfan syndrome, while mutations in the gene for fibrillin-2 cause Congenital Contractural Arachnodactyly." (PMID 26114882, 2015). "Fibrillin-1 gene mutations also cause Marfan Syndrome (MFS) (OMIM number 154700) and many of the characteristics of WMS and MFS have been attributed to aberrant TGF-β signaling." (PMID 26263555, 2015). "Mutations in FBN1 are associated with a wide phenotypic spectrum ranging from classic features of Marfan syndrome presenting in childhood and early adulthood to severe neonatal presentation." (PMID 26444669, 2015). "Marfan syndrome is mostly caused by mutations within the gene encoding fibrillin 1 (FBN1), the major component of connective tissue microfibrils." (PMID 24804794, 2014). "Several inherited connective tissue disorders are linked to mutations in the human FBN1 gene, which encodes fibrillin-1: for example, Marfan syndrome, stiff skin syndrome, acromicric and geleophysic dysplasias and Weill-Marchesani syndrome." (PMID 23264024, 2014).
Marfan syndrome (continued). "The co-occurrence of lung emphysema and vascular abnormalities in association with deregulated TGF-β signaling has also been shown in another mouse model with a deficiency in an ECM protein, Fibrillin-1, which is a model for Marfan syndrome." (PMID 25255451, 2014). "Marfan syndrome is a rare AD disorder of connective tissue (OMIM #154700) due to mutations in the gene encoding for fibrillin-1 (FBN1) located on chromosome 15." (PMID 25101051, 2014). "Marfan syndrome is a monogenic connective tissue disorder, caused by mutations in the gene encoding fibrillin-1 (FBN1)." (PMID 25238161, 2014). "Classically, pathogenic mutations in the FBN1 gene result in Marfan syndrome, a multisystem disorder that includes the musculoskeletal abnormality of scoliosis." (PMID 25504735, 2014). "Marfan's syndrome is a systemic disorder of the connective tissue caused by mutations in the extracellular matrix protein fibrillin-1, with aortic dissection and aneurysm being its most life-threatening manifestations." (PMID 24093072, 2013). "This is the first report of a patient with Marfan syndrome that is caused by a confirmed FBN1 mutation with associated pigmentary glaucoma." (PMID 23444230, 2013). "Fibrillin microfibrils are also present in the arterial wall to maintain the elasticity which is usually lost in Marfan syndrome, where a fibrillin-1-encoding gene (FBN1) mutation fosters aortic dilatation and dissection." (PMID 23962393, 2013). "An interesting phenotype of neonatal progeroid features, Marfan syndrome and generalised lipodytrophy (Wiedemann-Rautenstrauch syndrome) has recently been described in association with FBN1 mutations located in the C-terminal domain of the protein." (PMID 24348270, 2013). "Mutations in the fibrillin-1 gene FBN1 produce vascular defects that are clinically associated with Marfan syndrome." (PMID 24312398, 2013). "Fbn1 encodes the extracellular matrix protein fibrillin-1, and its mutation results in the dominant connective tissue disease Marfan syndrome." (PMID 23593401, 2013). "Marfan syndrome is associated with ventricular arrhythmia but risk factors including FBN1 mutation characteristics require elucidation." (PMID 24349050, 2013). "It has long been appreciated that FBN1 mutations are associated with vastly different phenotypes ranging from Marfan syndrome and Weil–Marchesani syndrome to isolated ectopia lentis." (PMID 23444230, 2013). "Our report strengthens the association of pigmentary glaucoma with Marfan syndrome that is caused by fibrillin-1 mutation." (PMID 23444230, 2013). "Marfan syndrome is caused by a defect, or mutation, in the gene that determines the structure of fibrillin-1, a protein that is an important part of connective tissue." (PMID 23915457, 2013). "The P1148A substitution in FBN1 gene was initially thought to be a pathogenic mutation causing Marfan syndrome in the majority of patients of Asian descent." (PMID 26316991, 2013). "We report here on a patient with Marfan syndrome caused by a novel truncating mutation in FBN1 with associated pigmentary glaucoma, a form of open angle glaucoma accompanied by dispersion of iris pigment." (PMID 23444230, 2013). "Mutations in FBN1 are known to cause Marfan’s syndrome and have been associated with tissue stability." (PMID 22648066, 2013). "We performed an observational cohort study of 80 consecutive adults (30 men, 50 women aged 42±15 years) with Marfan syndrome caused by FBN1 mutations." (PMID 24349050, 2013). "Marfan syndrome patients with fibrillin-1 mutations have a tooth phenotype, and a hypomorphic fibrillin-1 mouse model displays a periodontal ligament phenotype." (PMID 23931052, 2013). "The FBN1 mutation found in this study is a truncation mutation, which usually is associated with more severe Marfan syndrome phenotypes." (PMID 23444230, 2013).
Marfan syndrome (continued). "Mutations in FBN1 are mainly responsible for the Marfan syndrome (MFS), recognized by its pleiotropic clinical features including tall stature and arachnodactyly, aortic dilatation and dissection, and ectopia lentis." (PMID 22242013, 2012). "Mutations in the Fibrillin-1 gene result in a complex connective tissue disorder called Marfan syndrome with prevalent cardiovascular, ophthalmologic and orthopaedic signs." (PMID 23055981, 2012). "Most mutations in fibrillin-1 cause Marfan syndrome with severe cardiovascular and ocular symptoms, and tall stature." (PMID 23133647, 2012). "Mutations of the FBN1 gene, which encodes fibrillin-1, are associated with the development of Marfan's syndrome." (PMID 23198270, 2012). "Children affected by the Marfan syndrome carry a mutation in one of their two copies of the gene that encodes the connective tissue protein fibrillin-1 (FBN 1)." (PMID 23304566, 2012). "In the Human Gene Mutation Database (HGMD), 782 different mutations have been documented for the FBN1 gene, of which 669 are related to Marfan Syndrome." (PMID 23493941, 2012). "A mutation in the FBN1 gene has been reported in neonatal Marfan syndrome associated with emphysema." (PMID 22276220, 2012). "Numerous mutations in fibrillin-1 cause Marfan syndrome, a severe inherited disease associated with long limbs and major cardiovascular and lens defects." (PMID 23133647, 2012). "Children affected by the Marfan syndrome carry a mutation in one of their two copies of the gene that encodes the connective tissue protein fibrillin-1." (PMID 23304566, 2012). "Of note, targeted deletion of Fbn1 in mice phenocopies the defects observed in Marfan syndrome indicative of a causal relationship between FBN1 mutations and valve malformation." (PMID 22701807, 2012). "The majority of Marfan syndrome (MFS) cases is caused by mutations in the fibrillin-1 gene (FBN1), mapped to chromosome 15q21.1." (PMID 22260333, 2012). "Marfan syndrome (MFS) is caused by mutations in the fibrillin-1 (FBN1) gene, and mutations in FBN1 are known to be responsible for over 90% of all MFS cases." (PMID 22300218, 2012). "Of note, a mutation in FBN1, which encodes an extracellular matrix glycoprotein, has been associated with the coexistence of Marfan’s Syndrome and ankylosing spondylitis." (PMID 23259760, 2012). "Three patients of the one family who met clinical diagnostic criteria for Marfan syndrome had a 542 Kb deletion in chromosome 15 including the whole FBN1 gene; the study of the region was refined by MLPA and array analysis." (PMID 22260333, 2012). "For instance, Marfan syndrome is believed to result from mutations in the gene encoding fibrillin-1." (PMID 22128246, 2011). "One patient had a clinical diagnosis of Marfan syndrome, which was confirmed by a pathogenic mutation in the FBN1 gene (c.3757C>T, p.Gln1253X)." (PMID 21089071, 2011). "In our study, we identified two novel large deletions in the FBN1 gene in four patients of two unrelated families who met clinical diagnostic criteria for Marfan syndrome." (PMID 21936929, 2011). "The disorders caused by FBN1 mutations are classified as Marfan syndrome and type 1 fibrillinopathies, which include Marchesani syndrome (MASS), isolated ectopia lentis, isolated skeletal features of MFS, and thoracic aortic aneurysms." (PMID 22219643, 2011). "Our result expands the mutation spectrum of FBN1 and contributes to the study of the molecular pathogenesis of Marfan syndrome." (PMID 21976953, 2011). "Marfan syndrome (MFS) is an autosomal dominant inherited disorder of connective tissue that is caused by mutations in the gene for fibrillin-1 (FBN1), with prominent clinical manifestations in the cardiovascular, skeletal and ocular systems." (PMID 21647416, 2011). "Mutations in fibrillin-1 cause fibrillinopathies of which the most well known is Marfan syndrome, which sometimes includes megalocornea and usually includes ectopia lentis without complete lens dislocation." (PMID 22025892, 2011).
Marfan syndrome (continued). "We identified two novel large deletions in the FBN1 gene in four patients of two unrelated families who met clinical diagnostic criteria for Marfan syndrome." (PMID 21936929, 2011). "FBN2 mutations are responsible for many cases of CCA while mutation of the related gene FBN1 can result in Marfan's syndrome." (PMID 20161761, 2010). "Only one family has been reported in which Marfan syndrome was found in two affected cousins homozygous for a FBN1 mutation while the four normal parents were heterozygous carriers, indicating recessive inheritance of the syndrome." (PMID 20886638, 2010). "Other possible candidates are the type V collagen genes COL5A1and COL5A2 involved in Ehlers-Danlos syndrome (EDS), fibrillin-1 gene (FBN1) responsible for Marfan syndrome, PAX6 associated with aniridia and FOXC1 associated with abnormal ocular development." (PMID 20485516, 2010). "Initially, it was assumed that the pathogenesis of bovine arachnomelia resembles that of human Marfan syndrome, which is caused by mutations in the FBN1 gene." (PMID 20865119, 2010). "Gene targeting in embryonic stem cells has been used to generate null alleles of Fbn1 and Fbn2 and both have proven to be partial but imperfect models of Marfan's syndrome and CCA respectively." (PMID 20161761, 2010). "Mutations in FBN1 can cause Marfan syndrome, a connective tissue disorder that results in a range of clinical manifestations, with the principal complications occurring in the eye and the skeletal and cardiovascular systems." (PMID 20360993, 2010). "Some of the earliest work was the discovery that mutation of Fibrillin 1 (FBN1) was the cause of Marfan syndrome, which is characterized by progressive aortic root dilation with a predisposition to dissection, lens dislocation, and skeletal anomalies." (PMID 21532774, 2010). "Having a parent, child or sibling with either:-presence of a mutation in FBN1known to cause Marfans syndromeor-presence of a haplotype around FBN1, inherited by descent, known to be associated with Marfan syndrome in the family." (PMID 19123951, 2009). "As a connective tissue disorder with autosomal dominant inheritance, Marfan syndrome is caused by loss-of-function mutations in fibrillin-1, a matrix component of extracellular microfibrils." (PMID 19742316, 2009). "Both Marfan syndrome and Marfan-related disorders mainly result from mutations in the fibrillin-1 gene (FBN1)." (PMID 19390640, 2009). "Our data further expand the mutation spectrum of FBN1 and help in the study of molecular pathogenesis of Marfan syndrome and Marfan-related disorders." (PMID 19390640, 2009). "If family history for Marfan syndrome is positive or FBN1 mutation has been found, then a major criterion in one organ system and involvement of another organ system is necessary for diagnosis." (PMID 20184697, 2009). "The phenotype of the TSK1 mouse, a model of scleroderma, results from a partial in-frame duplication of the FBN1 gene and defects in FBN1 are the cause of Marfan's syndrome (OMIM: 154700)." (PMID 18648520, 2008). "Beals syndrome has distinct features however, and is caused by a mutation in the fibrillin-2 gene (FBN2) in 5q23, while Marfan syndrome is caused by mutations in fibrillin-1." (PMID 16740166, 2006). "The genetic and biochemical defect of Marfan's syndrome is a mutation in the gene for fibrillin-1, an extracellular matrix protein involved in proper organization of fibrils." (PMID 16611357, 2006). "Mutations in the gene encoding fibrillin-1 have been documented for Marfan syndrome and some related disorders in humans, and for Tsk in animals." (PMID 16277674, 2005). "For instance, premature termination codon variants in FBN1 (MIM: 134797) are associated with a higher risk of aortic dissection in Marfan syndrome (MIM: 154700), but individuals with other categories of variants may also experience aortic dissection." (PMID 41443197, 2026).
Marfan syndrome (continued). "Notably, in some genetic aortic diseases such as Marfan syndrome (characterized by FBN1 mutation) and Loeys–Dietz syndrome (characterized by TGFBR1/2 mutations), excessive activation of the TGF-β signaling pathway has been observed." (PMID 40948935, 2025). "Pathogenic variants in FBN1 underlie Marfan syndrome, while FBN2 is implicated in congenital contractural arachnodactyly and may modify risk in syndromic or nonsyndromic arteriopathies." (PMID 40981152, 2025). "LAMA2 mutations are also known to be associated with muscular dystrophy, while FBN1 mutations are linked to connective tissue abnormalities, including Marfan syndrome, which may also lead to scoliosis." (PMID 39926328, 2025). "Marfan syndrome is caused by a mutation in the FBN1 gene encoding fibrillin-1." (PMID 40497939, 2025). "Mutations in FBN1 are linked to autosomal dominant Weill-Marchesani syndrome and Marfan syndrome." (PMID 40144770, 2025). "Genetic loss of TGF-β signaling significantly slowed myxomatous changes, but blockade of monocyte recruitment failed to prevent myxomatous changes conferred either by loss of KLF2/4 or by expression of the mutant FBN1 C1039G protein associated with Marfan syndrome." (PMID 40519164, 2025). "However, overactivity of TGF-β signaling pathway was observed in the Marfan syndrome (MFS) mouse model induced by Fbn1 mutation." (PMID 40948935, 2025). "The FBN1 gene, associated with Marfan syndrome, was the first HTAD gene identified." (PMID 41463310, 2025). "Marfan syndrome (FBN1 mutations) was observed in 45% (95% CI 40–50%) of all aortic aneurysms." (PMID 40110250, 2025). "Defects in FBN1 cause Marfan syndrome, which is also associated with TAA38." (PMID 39956831, 2025). "It is worth mentioning that opposite muscle phenotypes have been observed in patients with mutations in the same gene, notably in FBN1, where some mutations cause WMS, featuring a (pseudo)muscular built, whereas most FBN1 mutations cause Marfan syndrome, which is characterized by low muscle mass." (PMID 41034152, 2025). "Marfan syndrome is an autosomal dominant syndrome that involves variants in the FBN1 gene pathogenic to biological activities that cause the synthesis of fibrillin-1, which is a fundamental structural protein involved in connective tissue integrity in all parts of the body." (PMID 41541920, 2025). "The FBN1 gene, causative for Marfan syndrome, is a major component of connective tissue microfibrils glycoprotein and it works as an important calcium binding microfibrillar structural molecule and serves as a regulator of TGF-β signaling involving the structure of elastic and non-elastic tissues." (PMID 41010011, 2025). "Historically, the understanding of heritable TAAD was anchored in syndromic disorders such as Marfan syndrome (caused by pathogenic FBN1 variants) and LDS (linked to TGFBR1, TGFBR2, SMAD3, SMAD2, TGFB2, and TGFB3), conditions defined by clear Mendelian inheritance patterns and systemic features." (PMID 40981152, 2025). "Other connective tissue disorders, such as fibrillin-1 deficiency in Marfan Syndrome, could affect TGF-β signaling." (PMID 40274989, 2025). "In contrast, a patient with FBN1-associated Marfan syndrome may require lensectomy due to progressive lens subluxation despite having no ‘cataract’." (PMID 41465105, 2025). "FBN1 germline alterations have been previously associated with Marfan syndrome." (PMID 41149474, 2025). "No predicted damaging variants were identified in the coding regions of FBN1 (known to cause Marfan syndrome when mutated); however, a novel variant was found that is predicted to alter splicing in FBN1 (chr15:48780559:A>C, predicted splice donor gain), which was not carried by the SCAD proband." (PMID 40194966, 2025). "Two patients with FBN1 gene variants showed the characteristics of Marfan syndrome." (PMID 38256594, 2024). "Pathogenic variants in the FBN1 gene are the main cause of Marfan syndrome (OMIM: 154700)." (PMID 39125885, 2024).